RN7SL797P (RNA, 7SL, cytoplasmic 797, pseudogene)
Gene: Miscellaneous RNA gene on chromosome 6 (96,282,567 to 96,282,863, forward strand). Ensembl gene ENSG00000242560.
Homologues: Orthologues: chimpanzee Metazoa_SRP (99% identical), macaque Metazoa_SRP (95% identical). Paralogues in human: RN7SL1 (85% identical), RN7SL2 (85% identical), RN7SL3 (85% identical), RN7SL804P (84% identical), RN7SL589P (82% identical), RN7SL296P (82% identical), RN7SL451P (82% identical), RN7SL655P (82% identical), RN7SL492P (82% identical), RN7SL14P (81% identical), RN7SL220P (81% identical), RN7SL408P (81% identical), and 705 more.